GPX3 (glutathione peroxidase 3)
Diseases named in the same sentence as GPX3 in open-access papers (continued):
Sharing a sentence is not in itself a finding about the gene and the disease.
tumor (continued). "In addition, as a secretory GPX member, the relationship between GPX3 and the tumor microenvironment has not been discussed." (PMID 36845676, 2023). "Furthermore, both in rats as well as humans, GPX3 was also observed to be down-regulated in all grades of endometrial adenocarcinoma, irrespective of tumor grade." (PMID 30469536, 2018). "We propose a model of CISD2–ROS–EGR1/GPX3 axis signaling, in which increased levels of CISD2 contribute to the neutralization of excessive ROS production, which would otherwise increase antitumor activity mediated at least by the tumor suppressors EGR1 and GPX3." (PMID 28928421, 2017). "Using the Pearson correlation statistical analysis, we did not detect significant correlation between downregulation of GPX3 mRNA and patients clinical-pathological properties (tumor size, tumor grade, and number of axillary metastatic lymph nodes) in non-IBC and IBC patients." (PMID 24790704, 2014). "In addition, methylation silencing of GPX3 in IBC may contribute to invasion of IBC carcinoma cells into lymphatic vessels, formation of tumor emboli, and IBC chemoresistance as suggested in other cancers." (PMID 24790704, 2014). "To explore whether GPX3, DIO1, and LRRC19 still correlate when including the normal tissue samples, we performed correlation analysis in the datasets of “523 TCGA tumor cases + 72 TCGA normal cases” and “523 TCGA tumor cases + 72 TCGA normal cases + 28 GTEx Kidney-Cortex cases”." (PMID 32316597, 2020). "The GPX3 and TXNRD1 genes had the strongest negative and positive correlation with the tumor stemness, respectively." (PMID 33706760, 2021). "The transcription levels of GPX3 and DIO1 were significantly lower in KIRC patients than normal control cases in subgroup analysis based on gender, age, tumor grade, and nodal metastasis status." (PMID 32316597, 2020). "Results showed that GPX3 methylation was detected in 77.1% (162/210) of RCC tumors, but only 14.6% (7/48) in adjacent non-malignant renal tissues, suggesting tumor-specific methylation of GPX3 in RCC." (PMID 25970749, 2015). "Through a literature survey, we identified that GPX3, LDOC1, LXN, and UCHL1, but not LIPG, have been reported as tumor suppressor genes, and that their expression was mediated by promoter DNA methylation." (PMID 26317789, 2015). "We found that the expression of GPX3 was uniformly down regulated in both rat and human EAC, regardless of tumor grade or histopathological subtype, implying that the down-regulation is an early event in EAC." (PMID 21106063, 2010). "Thirteen of the EAC samples the Gpx3 promoter were biallelically methylated, One tumor, NUT39, showed monoallelic methylation and Gpx3 was therefore not as much down-regulated in this tumor as in the tumors with biallelic hypermethylation, which was also confirmed in the expression analysis." (PMID 21106063, 2010).
cancer (111 papers, 2010 to 2025). A tumor composed of atypical neoplastic, often pleomorphic cells that invade other tissues. "Knockout models of GPx3 have revealed that its loss promotes cancer initiation, particularly when combined with genetic alterations or carcinogenesis models." (PMID 39942544, 2025). "GPx3 is frequently hypermethylated in various cancers, and this downregulation is linked to poor prognosis and resistance to chemotherapy." (PMID 39942544, 2025). "The specific mechanism by which GPX3 affects cancer susceptibility to chemotherapy also needs further study." (PMID 36845676, 2023). "Survival analysis showed that GPX3 expression was associated with the survival of multiple human cancers." (PMID 36845676, 2023). "The result showed that the GPX3*TC + CC variant is a significant risk factor for the development of BEN-associated carcinoma." (PMID 37629712, 2023). "Many studies have found that the down-regulation of the GPX3 gene in various cancers is caused by promoter methylation." (PMID 33706760, 2021). "Previous studies suggested that GPX3 prevented the colitis-associated carcinoma by immunomodulation." (PMID 33767290, 2021). "These SNPs are primarily found in non-coding regions of the GPX3 gene and their positive association with increased cancer risk is primarily thought to be due to their effects on GPx3 mRNA down-regulation." (PMID 32781581, 2020). "In many of these cancers, downregulation of GPx3 parallels cancer progression, and is often associated with poor patient outcome." (PMID 32781581, 2020). "We highlight several studies in Section 3.2 where GPx3 has been implicated in modulating the activity of redox signaling pathways in cancer cells." (PMID 32781581, 2020). "While low Se levels likely contribute to decreased plasma GPx3 expression by the kidney in cancer patients, the precise mechanisms contributing to Se depletion and plasma GPx3 loss are still unclear." (PMID 32781581, 2020). "Many studies report that downregulation of GPx3 in many types of human cancer is caused by promoter hypermethylation." (PMID 30260967, 2018). "Hypermethylation of the GPX3 promoter reduces expression of this gene, which is associated with the mechanism of drug resistance and the shorter survival of cancer patients." (PMID 26682223, 2015). "CO1 and COX3 genes have been extensively utilized in polymorphic and phylogenetic analysis in some species and GPX3 is associated with certain cancers." (PMID 26426260, 2015). "In such types of cancer, the chronic inflammation is always inevitable and would cause the lower level of GPx3 expression." (PMID 25333265, 2014). "Studies showed that inhibition of glutathione peroxidase-3 (GPX3) was associated with cancer progression." (PMID 24790704, 2014). "Paradoxically, GPX3 inhibition is suggested to be associated with different stages of cancer progression including initiation, promotion, and metastasis." (PMID 24790704, 2014). "Further studies are necessary to confirm this finding using alternative assays and to elucidate the underlying mechanisms of how GPX3 potentially regulates cancer metastasis." (PMID 23071548, 2012). "A likely consequence of loss of GPX3 protein function would be a higher amount of ROS in the cancer cell environment." (PMID 21106063, 2010). "The upregulation of GPX3 mRNA following SELENOV treatment may also be associated with suppression of F9 cancer cell proliferation." (PMID 41463386, 2025). "Polymorphisms of the gene encoding GPX3 are often responsible for the downregulation of gene transcription, resulting in markedly decreased plasma activity of GPX3, and are positively associated with cancer development." (PMID 39125992, 2024). "The downregulation of GPx3 expression is closely associated with cancers." (PMID 38732573, 2024). "Loss of GPx3 has been observed in the stomach, prostate, skin, and other cancers." (PMID 38483584, 2024).
cancer (continued). "However, GPX3 has also been implicated in metastasis and cancer progression in ovarian, kidney, and thyroid cancers." (PMID 36845676, 2023). "Besides, GPX3 was associated with pathways relating to cancer progression and immunosuppression, such as Wnt and TGF-β." (PMID 36845676, 2023). "These suggested that higher GPX3 expression levels may be associated with early metastasis of human cancers, including COAD, READ, BRCA, BLCA, KIRP, OV, and KICH." (PMID 36845676, 2023). "Hypermethylation of GPX3 has also been reported as a cancer risk factor." (PMID 32763516, 2020). "GPX3 loss in the plasma of cancer patients is often associated with poor patient outcome." (PMID 33050144, 2020). "In cancer patients with metastatic disease, low Se levels and plasma GPx activity have been associated with enhanced lipid peroxidation, suggesting that loss of GPx3 contributes to systemic oxidative stress." (PMID 32781581, 2020). "However, it is still unclear if systemic GPx3 loss is a major contributing risk factor for cancer development in response to other pro-tumorigenic stimuli, such as chronic inflammation and ionizing radiation." (PMID 32781581, 2020). "For example, GPX3 could suppress the development of colitis-associated carcinoma via inhibiting ROS production." (PMID 32735635, 2020). "So far, it has been shown that changes in the activity of the GPX1, GPX2, and GPX3 isoforms may be associated with the development of cancer." (PMID 26682223, 2015). "Diagnostic potential of GPX3: As an extracellular protein, GPX3 is readily detectable in blood, making it a promising biomarker for diagnosing diseases, assessing disease progression, and informing therapeutic decisions, for conditions such as cancer, IBD, inflammatory diseases, and ALS." (PMID 38927092, 2024). "However, the mechanism underlying GPx3-mediated suppression of cancer cell growth is unclear." (PMID 30260967, 2018). "Selenoproteins, particularly GPx1, GPx3, TrxR, SELENOP, SELENOM, SELENOS, SPS1, and SPS2, are essential in regulating oxidative stress and cancer risk." (PMID 39942544, 2025). "In ovarian cancer, GPX3 has been reported to support cancer progression by modulating the extracellular redox environment." (PMID 40092686, 2025). "The observed decrease in GPx3 activity in GC patients is in accordance with the increased production of ROS typical of cancer." (PMID 39897791, 2025). "For instance, C1QTNF3 regulates inflammatory pathways, NEU1 modulates cellular signaling and shows therapeutic potential for cancer and immune disorders, and GPx3 is known for its antioxidant and anti-inflammatory properties." (PMID 40243471, 2025). "Oral IAA administration can modulate reactive oxygen species (ROS)-degrading enzymes such as glutathione peroxidase 3, thereby decreasing the accumulation of ROS in cancer cells." (PMID 40423900, 2025). "GPX3 typically exhibits differential expression patterns across various cancers, with promoter hypermethylation commonly observed in most tumors, including TC." (PMID 40092686, 2025). "The most central protein, fatty acid-binding protein 1 (FABP1), was found to be upregulated in cancer tissues with low GPx3 expression." (PMID 38732573, 2024). "The median gene expression of GPx3 in cancer tissues was 38.489, which was significantly lower compared to 401.971 in normal tissues." (PMID 38732573, 2024). "Among these kinds of solid cancer, GPX3 can not only play a cancer-promoting role, but also play a cancer-suppressing effect." (PMID 38774759, 2024). "Extracellular glutathione peroxidase (GPX3) was downregulated in cancer samples but was upregulated in the cluster 2 patients with higher TME content and metabolic activity, and is considered a prognostic gene in gastric patients." (PMID 38962317, 2024). "Since the implications of GPX3 in cancer have been well documented and extensively reviewed, this issue is beyond the scope of this paper, and this paper will focus primarily on its roles outside of oncology." (PMID 38927092, 2024).
cancer (continued). "In early-stage cancer and precancerous lesions, decreased expression of GPX3 and increased ROS production promote cancer development." (PMID 39125992, 2024). "Through the CIBERSORT, MCPcounter, TIMER, and xCELL algorithms and online websites, we carefully analyzed the relationship between GPX3 expression levels in human cancers and immune score, stromal score, and various cell components in the TME." (PMID 36845676, 2023). "GPX3 knockdown resulted in a significant increase in cancer cell sensitivity to platinum-based drugs." (PMID 36845676, 2023). "We used the TCGA database to examine the relationship between GPX3 expression and the pathological stages of human cancer." (PMID 36845676, 2023). "For the T-stage, GPX3 played an inconsistent role in different types of cancer, possibly because of the difference in mRNA and protein data from several sources." (PMID 36845676, 2023). "In this study, we used multiple human cancer cell lines to examine the effect of GPX3 on metastasis." (PMID 36845676, 2023). "This suggested that higher DNA methylation in the GPX3 promoter region leads to its lower expression levels in cancer." (PMID 36845676, 2023). "In this study, we found that downregulated GPX3 significantly increased the sensitivity of cancer cells to cisplatin, while oeGPX3 promoted the resistance of cancer cells to chemotherapy." (PMID 36845676, 2023). "We explored the correlation between GPX3 expression and chemotherapy sensitivities in cancer cell lines." (PMID 36845676, 2023). "A burgeoning body of evidence indicates that GPX3 plays a crucial role in the proliferation and development of human cancers 24-30." (PMID 37790850, 2023). "Knockdown of Gpx3 and Gpx7 in cancer cells was sufficient to increase the accumulation of ROS after treatment with FIRINOX, and increased the susceptibility of the cancer cells to FIRINOX to a similar extent as 3-IAA and FIRINOX." (PMID 36813961, 2023). "In most cancer types, the expression level of GPX3 was positively correlated with the stromal score and immune score." (PMID 36845676, 2023). "We explored the relationship between GPX3 and clinical features, immune infiltration characteristics, migration and metastasis, and chemotherapy sensitivities of human cancers." (PMID 36845676, 2023). "Overall, pan-cancer analysis of GPX3 illustrated the prospect of GPX3 expression in the prognosis, chemotherapy sensitivity, and immune infiltration of several types of human cancers, providing diagnostic and prognostic biomarkers." (PMID 36845676, 2023). "Overall, more studies are needed to determine the role of GPX3 in cancer occurrence, progression, or metastasis." (PMID 36845676, 2023). "In early cancer and precancer, the expression of GPX3 is decreased and the production of ROS is increased to promote cancer occurrence." (PMID 36845676, 2023). "However, how GPX3 affects cancer patients’ outcomes and the underlying mechanism remains unclear." (PMID 36845676, 2023). "Most of these CAF-related genes are associated with tumorigenesis and cancer progression, including GLT8D1, GPX3, NRP1, PPP1R26, SERPINE1, and TMSB15A." (PMID 36717783, 2023). "Next, the K-M survival curves demonstrated the prognostic status in the high- and low-expression groups of CALB2 and GPX3 in 26 cancers." (PMID 37664836, 2023). "According to our findings, the GPX3 expression is markedly decreased in most cancers, while MMP1 and MMP12 expression was distinctly upregulated in most types of tumors." (PMID 36081670, 2022). "Studies have shown that GPX3 plays a role in a variety of cancers, including ovarian cancer, breast cancer, and thyroid cancer." (PMID 35340708, 2022). "We conducted pan-cancer assays based on TCGA datasets to investigate the putative roles of GPX3, MMP1, and MMP12 in malignancies." (PMID 36081670, 2022). "When GPX3 is administered to mice, cancer metastasis is prevented, but further research is needed to determine how this is accomplished." (PMID 35069731, 2022).
cancer (continued). "In general, the GPX3 gene showed a down-regulation trend in all types of cancers except for GBM, while the other six genes were up-regulated or down-regulated according to the specific type of cancer." (PMID 33706760, 2021). "The GPX3 gene is therefore likely to be a promising target for cancer therapy, but more robust evidence is needed to elucidate its anticancer mechanisms and the conditions in which it can be applied." (PMID 33706760, 2021). "On the contrary, there are a number of preclinical studies investigating the effect of the positive modulator of GPx-3 in cancer cells that exhibit the ability to inhibit the proliferation and metastatic behavior." (PMID 33505588, 2021). "In all types of cancer, the GPX3 gene was mainly negatively correlated with RNAss, which this conclusion also made for the correlation between this gene and DNAss." (PMID 33706760, 2021). "Only one antioxidant protein, GPX3, was altered by cancer development (~70% lower in experimental groups)." (PMID 33105841, 2020). "Antioxidant enzymes often display dichotomous expression and have context-dependent roles within cancer cells, which are similarly observed for GPx3." (PMID 32781581, 2020). "In cancers that display low GPx3 expression, hypermethylation of the GPX3 promoter has been demonstrated as a mechanism for GPx3 downregulation, which is further discussed in Section 3.2." (PMID 32781581, 2020). "High-risk genes in the model, including GPX3, AKR1C4, SPHK1and ADCY5, have been reported to promote hypermethylation, rare mutations, cancer progression, poor prognosis, and the developmental process of malignant cells in CRC patient samples or cell lines." (PMID 32953273, 2020). "Serum GPx3 level downregulation has been observed in many cancers, while its upregulation is connected to the suppression of tumorigenesis." (PMID 33255360, 2020). "To date, studies of selenoproteins raised on the association between Se supplements and cancer prevention, as well as GPX1, GPX2, and GPX3, have been reported with major physiological roles of cancer prevention or development." (PMID 32316597, 2020). "GPx3 promoter hypermethylation specifically downregulates its expression, which occurs commonly in human cancers, including prostate, gastric, breast, lung, and colon cancers." (PMID 32380763, 2020). "GPx3 is mainly synthesized in the proximal tubules of the kidney and is usually down-regulated in cancer tissues." (PMID 28837649, 2017). "It has also been reported that GPx3 promotes hypermethylation, and its down-regulation is commonly observed in human cancers." (PMID 28837649, 2017). "GPX3 belongs to the family of glutathione peroxidases, the most important ROS scavengers, and its expression is suppressed in a variety of cancers." (PMID 27489351, 2016). "PIG3 has also been reported to mediate cancer cell death induced by glutathione peroxidase 3 (GPx3), with depletion of PIG3 or mutation of the PIG3 binding motif in GPx3 abrogating the increases in ROS and caspase-3 activity that are normally observed." (PMID 25797244, 2015). "Evidence of hypermethylation at the CpG island associated with ZNF300P1 was observed in both cancer cell lines, however hypermethylation of neighboring CpG islands (ZNF300 and GPX3) was only observed in A2780 cells." (PMID 24393131, 2014). "For each carcinoma tissue specimen, the band intensity of the methylated and unmethylated GPX3-MSP products was quantified and normalized against gel background." (PMID 24790704, 2014). "The present results are consistent with other studies which proved that GPX3 is downregulated in carcinoma tissues such as prostate, thyroid, and esophageal." (PMID 24790704, 2014). "Sep15 and GPx3 are additional selenoproteins which have substantial roles during cancer development." (PMID 23977205, 2013). "We observed that 39% (9/23) of the normal gastric tissues adjacent to cancers showed an increased DNA methylation level of the GPX3 promoter from 10% to 15%." (PMID 23071548, 2012).